NLRP3 (NLR family pyrin domain containing 3)
Diseases named in the same sentence as NLRP3 in open-access papers (continued):
Sharing a sentence is not in itself a finding about the gene and the disease.
infection (continued). "In previous work, adenovirus was shown to activate the NLRP3 inflammasome at early time points of infection through TLR9 sensing the virus double-stranded DNA after endosomal membrane penetration." (PMID 31849970, 2019). "Wild-type and NLRP3-knockout J774A.1 macrophages were infected with NG, and the number of engulfed bacteria was determined 4 h after infection by colony-forming unit (CFU) assay." (PMID 31417575, 2019). "There are several implications of the finding that the level of expression of NLRP3, NLRP12, and IFI16 inflammasomes is increase following infection virulent HSV-1 strains and this was associated with severe corneal inflammatory herpetic disease." (PMID 31367214, 2019). "To confirm association of NLRP3, NLRC4 and NAIP with ASC during CFT073 infection of THP-1m, we performed immunoprecipitation of ASC and detected NLRP3, NLRC4 and NAIP proteins." (PMID 31551961, 2019). "The activation of the NLRP3 inflammasome is an important part of innate immunity against pathogen infection." (PMID 30858838, 2019). "When infection experiments were performed in the presence of glyburide, a compound that inhibits NLRP3 inflammasome, or A151, a specific AIM2 inhibitor, the secretion of IL-1β was significantly inhibited with respect to uninfected controls." (PMID 32038610, 2019). "Cells were harvested at 2, 8, and 24 h post-infection and the level of expression of NLRP3, NLRP6, NLRP12, IFI16, and AIM2 was determined by western blot." (PMID 31367214, 2019). "NLRP3 inflammasomes are molecular platforms that are activated upon cellular infection or stress that triggers pyroptotic cell death." (PMID 31824415, 2019). "In contrast, the induction of fecal Lcn-2 observed in MNV-infected Stat1-/- mice at three days post-infection was significantly diminished in both Stat1-/-Nlrp3-/- and Stat1-/-Gsdmd-/- mice." (PMID 31017981, 2019). "During early infection with EV71 in mice, brain tissue from NLRP3-inflammasome-deficient showed decreased levels of IL-1β." (PMID 30858838, 2019). "The NLRP3 inflammasome senses infection of some DNA viruses and RNA viruses like adenovirus, vesicular stomatitis virus (VSV), or influenza virus." (PMID 31024004, 2019). "IL-1β secretion upon NLRP3 inflammasome activation initiates acute phase reactions, including the recruitment of inflammatory cells at the site of infection and expression of proinflammatory cytokines, such as, IL-6, TNF-α, and chemokines." (PMID 31590215, 2019). "Accumulating evidence has demonstrated that excessive activation of the NLRP3 inflammasome mediates lung injury induced by infection, hyperoxia, and mechanical ventilation." (PMID 30937316, 2019). "In response to pathogen infection and tissue damage, pattern recognition receptors (PRRs) (NLRP3, NLRC4) oligomer is formed and it can recruit ASC." (PMID 31133717, 2019). "To determine the role of caspase-1 and NLRP3 in IL-1β secretion by B. abortus-infected LX-2 cells, we performed the infection of LX-2 cells in the presence of specific pharmacological inhibitors." (PMID 32038610, 2019). "As expected, KCl, but not NaCl treatment inhibited IL-1β and Casp1 p20 production in response to infection, confirming the participation of the NLRP3 inflammasome in human cells." (PMID 31754185, 2019). "Our previous studies show that NLRP3 constrains type 2 responses during infection with the gut-dwelling helminth parasite Trichuris muris, with a major effect on the development of adaptive Th2 cell immunity." (PMID 31586037, 2019). "NO acts as a critical negative regulator of the NLRP3 inflammasome in human monocytes and mouse BMFs and is known to play an important role in host resistance to infection, particularly to Leishmania spp parasites." (PMID 30736736, 2019). "We previously showed that IL-1β production via the NLRP3 inflammasome is critically required to control CP growth to successfully resolve the infection in mice." (PMID 31031755, 2019).
infection (continued). "A pro-inflammatory role of neutrophils in inflammation has also been identified in NLRP3 KO mice, but the behavior of neutrophils differs between NLRP3 KO models of infection and inflammation." (PMID 31270454, 2019). "Understanding how NG activates the NLRP3 inflammasome would help to reveal the inflammatory responses of gonorrhea and offer therapeutic strategies to treat infections." (PMID 31417575, 2019). "As a canonical activator of NLRP3 inflammasome, ATP can be released from both host tissue injury and bacterial cells during infection." (PMID 31906173, 2019). "Specifically, during the initial phase of infection, NLRP3 inflammasome is activated to produce IL-1β that promotes the recruitment of neutrophils and the onset of the inflammatory response." (PMID 31681274, 2019). "Significant increase of NLRP3 inflammasome positive dendritic cells in the spleen and liver after infection was detected only in WT mice." (PMID 31231399, 2019). "The major function of NLRP3 inflammasomes is to recognize a wide variety of danger signals that are due to exogenous infection and internal damage." (PMID 31174550, 2019). "Infection performed in macrophages derived from Nlrp3–/–, Aim2–/–, Asc–/–and Casp1/11–/–mice indicate that the NLRP3, but not AIM2 inflammasome is essential for production of inflammatory cytokines, such as IL-1β." (PMID 31479495, 2019). "For example, the mitochondrial antiviral signalling protein (MAVS), an adaptor protein in RNA sensing, is critical for NLRP3 inflammasome activation during infections with RNA viruses and stimulation with the synthetic RNA polyinosinic-polycytidylic acid." (PMID 31590215, 2019). "Together these data suggest that Syk signaling is critical for production of IL-1β and NLRP3 transcripts in T. gondii-infected primary human monocytes, and therefore appears to act in the priming stage of IL-1β production during infection." (PMID 31449558, 2019). "The NLRP3 inflammasome can be activated in response to infection or sterile inflammation mediated by endogenous DAMPs and ROS." (PMID 31824415, 2019). "Having demonstrated that infection with virulent HSV-1 strains increased NLRP3, NLRP12, and IFI16 inflammasome in infected human corneal epithelial cells, we next determined the level of expression of several components downstream of these inflammasomes." (PMID 31367214, 2019). "We found that these molecules did not influence the internalization of the parasites at 1 h after infection, but we detected an increased replication of L.g.− in Nlrp3−/− cells at 48 h after infection." (PMID 31754185, 2019). "Further studies indicated that IRF3 and IFNAR signaling during infections with intracellular bacterial pathogens that reside within phagosomes are required for caspase-11 expression and activation of the NLRP3 inflammasome and pyroptosis." (PMID 31134081, 2019). "In this study, the mRNA levels of TLR7 and NLRP3 were significantly increased in both infection groups (p < 0.05)." (PMID 31514454, 2019). "In our study, too, atypical NLRP3 activation by natural infection of MDMs by EPEC differed from caspase-4-signaling upon LPS transfection." (PMID 31018119, 2019). "Although the inflammasome is triggered by several viruses and plays an important role in the outcome of infections, our study is the first to identify the mechanisms of NLRP3 activation by an alphavirus." (PMID 31479495, 2019). "More recently, NLRP3 activation was also described in macrophages during longer term (16 hour) infection by Pseudomonas via the action of guanylate binding proteins." (PMID 30978238, 2019). "Infection and ROS activate NF-κB to mediate the expression of NLRP3 and increase the production of pro-IL-1β." (PMID 30779706, 2019). "In a final effort to establish a role for N. brasiliensis–induced inflammasome activation, we treated WT mice with MCC950, an NLRP3-specific inflammasome small molecule inhibitor, throughout the course of infection." (PMID 31586037, 2019).
infection (continued). "The ability of UPEC to modulate the NLRP3 inflammasome by α-hemolysin and type-1 fimbriae, as well as the diverse effects depending on the phase of infection, argues for great adaptability and survival tactics by UPEC." (PMID 29662840, 2018). "The need for such complex regulatory control of the NLRP3 inflammasome is likely due to the damaging consequences of unregulated NLRP3 activity in response to infection and also in auto-inflammatory diseases." (PMID 29674674, 2018). "Supporting this idea, a recent report described how TLR9 negatively regulates the NLRP3–IL-1β pathway in an infection model." (PMID 29774028, 2018). "Treatment of macrophages with FAC prior to infection exerted inhibitory effects towards the expression of Nlrp3 and resulted in less cleavage of both caspase-1 and downstream caspase-7 compared to the solvent." (PMID 29329289, 2018). "The components of the NLRP3 inflammasome are required for a normal host response to C. albicans in murine models of infection." (PMID 30065091, 2018). "Infection with Mtb bacilli is known to induce IL-1β both through inflammasome- (NLRP3) dependent and independent pathways." (PMID 29740038, 2018). "To exclude the possibility that macrophages and cDCs also contribute to early IFN-α and IFN-β production, we also depleted macrophages in Nlrp3−/− or Aim2−/− mice by intraperitoneal injection of clodronate liposome at 2 days before YM infection." (PMID 30470758, 2018). "Activation of the NLRP3 inflammasome during infection can be protective, but unregulated NLRP3 inflammasome activation in response to endogenous or exogenous stimuli can result in pathologic damage." (PMID 29747649, 2018). "Infection with Burkholderia pseudomallei or B. thailandensis triggers activation of the NLRP3 and NLRC4 inflammasomes leading to release of IL-1β and IL-18 and death of infected macrophages by pyroptosis, respectively." (PMID 29791511, 2018). "NLRP3 inflammasome activation is completely abrogated during acute infection (2 h) with T3SS mutant Pseudomonas." (PMID 30062052, 2018). "NLRP3 is able to sense both RSV and IAV infections resulting in increased NLRP3 expression in the lungs, as well as immune cells recruited to the site of infection." (PMID 29361733, 2018). "That is, NLRP3 inflammasome acts as a gatekeeper against pathogen infection, although uncontrolled inflammasome can induce disease." (PMID 30209319, 2018). "MAVS is known to mediate NF-κB and type I interferon signaling during infection with RNA viruses and require for the recruitment and optimal activation of the NLRP3 inflammasome." (PMID 30483252, 2018). "In this study, we focused on the role of the NLRP3 inflammasome in mediating the immune response against N. caninum at the acute stage of infection." (PMID 30105037, 2018). "Taken together, these data showed that infection of THP-1 cells with GRA15-intact T. gondii produced IL-1β in a manner dependent on NLRP3 and caspase-1; this led to an indirect reduction in IDO1 proteins, thereby supporting parasite growth in human cells." (PMID 30301855, 2018). "The development of lesions was observed, and biopsies of the injection site and various organs, including the kidney, liver, spleen, lung, and testis, were obtained for NLRP3, caspase-1, and interleukin-1β (IL-1β) mRNA analysis during infection." (PMID 29490620, 2018). "Another study also showed that the NLRP3 inflammasome pathway plays a critical role in the host immune response to pathogen infection." (PMID 30087667, 2018). "The role of caspase-1 in the killing of S. aureus, if Nlrp3−/− mice are protected from infection with this pathogen, is unclear." (PMID 29490278, 2018). "Infection of the NLRP3-lentiviral vector in DEFs also significantly inhibited bacteria growth (P < 0.01)." (PMID 30349536, 2018).
infection (continued). "The C. albicans ERMES mmm1 mutant shows delayed NLRP3 inflammasome response in a macrophage-Candida model of infection, with decreased ability of macrophage lysis and hence changing the outcome of the infection." (PMID 29261004, 2018). "The NLRP3 mRNA expression levels in the infection group showed a trend in elevation to decline in all five organs but was still higher than “normal” at the endpoint of the study (vs. the blank group, P < 0.05)." (PMID 29490620, 2018). "It has been demonstrated that infection with viral RNA and subsequent activation of the NLRP3 inflammasome is an important part of the host defense against IAV infection." (PMID 30013955, 2018). "First, we examined the macrophage NLRP3 inflammasome response using different NLRP3 triggers including infection with Sendai paramyxovirus (SeV)." (PMID 29855523, 2018). "Several danger signals such as ATP, alum hydroxide, silica crystals, urea crystals, nigericin, and infections with bacteria, viruses, and fungi activate the NLRP3 inflammasome." (PMID 30069026, 2018). "In this study, we focus on exploring the role of the NLRP3 inflammasome in the N. caninum-induced immune response in the acute phase of infection." (PMID 30105037, 2018). "To better understand the kinetics of the NLRP3 inflammasome activation, we investigated each component of NLRP3 inflammasome at different time-points after infection with T. gondii." (PMID 29291748, 2018). "During in vitro infections, IL-1β secretion was lower in alveolar macrophages from caspase-1/11, NLRP3 or AIM2 KO mice than in WT controls." (PMID 30456207, 2018). "Firstly, the duNLRP3 was successfully overexpressed in DEFs via the NLRP3-lentiviral vector infection." (PMID 30349536, 2018). "We infected BMDMs from C57BL/6, Casp11-/-, Casp1-/-Casp11Tg, Nlrp3-/- and Casp1/11-/- with B. abortus and after 17 hours of infection, we collected supernatant and measured IL-1α release." (PMID 30589883, 2018). "To further demonstrate the direct involvement of pDCs for early IFN-α and IFN-β production, we depleted pDCs in Aim2−/−, Nlrp3−/−, Casp1−/−, and Il1r1−/− mice by injection of anti-mPDCA-1 antibody at 12 h before and 12 h after infection." (PMID 30470758, 2018). "The NLRP3 inflammasome responds to infection and tissue damage, and rapidly escalates the intensity of inflammation by activating interleukin (IL)-1β, IL-18 and cell death by pyroptosis." (PMID 30069026, 2018). "In this study, we found that macrophage infection with LgyLRV1+ parasites resulted in the transcriptional up-regulation of several inflammasome components such as caspase-1, IL-1β, NLRP3, and AIM2." (PMID 29487860, 2018). "NLRP3 and NLRC4 together allow for the recognition of different danger signals from the same pathogenic infection." (PMID 29997616, 2018). "Total RNA was collected at 24 hours post infection for the detection of the transcript levels of NLRP3, caspase 1, IFNα and IFN inducible genes." (PMID 29167459, 2017). "We, for the first time, have shown that infection with South American (PRVABC59) or Nigerian (IBH30656) strains of ZIKV activated NLRP3 and caspase 1 in monocytes." (PMID 29167459, 2017). "The activation of NLRP3 inflammasome is regulated by two pathways in response to pathogen infection." (PMID 28060938, 2017). "NLRP3 is distinct from other core components because NLRP3 is activated by both DAMPs and PAMPs, while other core components are mainly activated by PAMPs and are involved in infection." (PMID 29259717, 2017). "The NLRP3 inflammasome senses and reacts to infection by numerous bacteria, viruses, fungi, and parasites, and this response can be protective for the host." (PMID 28558839, 2017). "In the context of infection, Staphylococcus aureus activates the NLRP3 inflammasome in human and rat conjunctival goblet cells." (PMID 28273882, 2017).
infection (continued). "In contrast, increased fungal recovery at weeks 2, 4, and 10 of infection were observed in the lungs of Nlrp3−/−, Casp1/11−/−, P2x7r−/−, and Asc−/− mice, that was more prominent at 10 weeks of infection." (PMID 28740491, 2017). "Since NLRC4 levels were significantly elevated compared with those of NLRP3 after infection, we focused on NLRC4." (PMID 28961278, 2017). "We have found that P. brasiliensis promoted a NLRP3 inflammasome-dependent caspase-1 activation to release the bioactive IL-1β, and IL-1R1−/− mice displayed a slightly increased survival rate to infection compared with the C57BL/6 mice." (PMID 28871251, 2017). "In the present study, the inhibition of NLRP3 inflammasome by infection with AAV8-shNLRP3, successfully attenuated collagen deposition and increased expression of TIMP-1 in the liver that had been induced by S. japonicum infection." (PMID 28808303, 2017). "NLRP3 oligomerizes through homotypic interactions between NACHT domains following the detection of pathogen infection or cellular stress." (PMID 28060938, 2017). "In agreement, an enhanced differentiation of Th17 and Tc17 cells were seen during the infection of NLRP3 sufficient mice." (PMID 28740491, 2017). "Infection of macrophages with Brucella abortus activates the NLRP3 inflammasome in a mechanism requiring IRE-1 mediated ER stress, mitochondrial damage and caspase-2 activity." (PMID 28570638, 2017). "The early and sustained activation of NLRP3 and IL-1β production contributes to the infiltration of neutrophils and monocytes to sites of infection where these cells continue to secrete cytokines resulting in a “cytokine storm”." (PMID 28418930, 2017). "The expression of the pattern-recognition receptors Nlrp3, Nlrp12, and Nlrp1a was significantly increased after infection." (PMID 28604600, 2017). "Although the NLRP3 inflammasome has been intensively investigated using cell culture, mouse genetic models, and various infection models, the signaling mechanism leading to NLRP3 inflammasome activation is still unclear." (PMID 28146092, 2017). "An increased influx of total leukocytes characterized as CD45+ cells was detected in the lungs of WT mice compared with Nlrp3−/−, Casp1/11−/−, and Asc−/− mice, which was more expressive in the acute phase (48 h) of infection." (PMID 28740491, 2017). "RIG-I (DDX58) is a key intracellular sensor for cytosol ssRNA and provides the transcriptional priming signal for NLRP3 inflammasome during infections with VSV and IAV, upon recognition of the vRNA." (PMID 29163496, 2017). "Our findings demonstrated that the genetic deficiency of NLRP3, Casp1/11, and Asc totally impaired the expression of IL-1β, IL-18, NLRP3, Casp1, and ASC mRNA in the lungs of infected mice at week 4 of infection." (PMID 28740491, 2017). "Infection with high dose of the fungus either intratracheally or intravenously, Nlrp3-/- mice had significantly less survival than wild type mice." (PMID 28671985, 2017). "Our data showed increased numbers of naïve CD4+ T cells in the lungs of Nlrp3−/−, Casp1/11−/−, and Asc−/− compared with WT mice at weeks 2, 4, and 10 of infection." (PMID 28740491, 2017). "Because human PCM is acquired by the pulmonary route of infection, in the present study, we sought to characterize the role of NLRP3 inflammasome in i.t. infected mice whose response involves pulmonary-mediated immunological mechanisms." (PMID 28740491, 2017). "We found that following infection of WT or NLRP3 deficient C57BL/6 mice with L. major, WT and NLRP3 deficient mice had similar lesion sizes." (PMID 28192528, 2017). "In this context pattern recognition receptors like TLR2, TLR4 and NLRP3 but also oxidative stress and antioxidant responses that are also responsible for infection defense play an important role." (PMID 30402600, 2017). "At 4 weeks of infection, less extensive and severe pulmonary lesions were observed in the lungs of WT in comparison with Nlrp3−/−, Casp1/11−/−, P2x7r−/−, and Asc−/− mice." (PMID 28740491, 2017).